IFIH1 (interferon induced with helicase C domain 1)
Description:
Innate immune receptor which acts as a cytoplasmic sensor of viral nucleic acids and plays a major role in sensing viral infection and in the activation of a cascade of antiviral responses including the induction of type I interferons and pro-inflammatory cytokines. Its ligands include mRNA lacking 2'-O-methylation at their 5' cap and long-dsRNA (>1 kb in length). Upon ligand binding it associates with mitochondria antiviral signaling protein (MAVS/IPS1) which activates the IKK-related kinases: TBK1 and IKBKE which phosphorylate interferon regulatory factors: IRF3 and IRF7 which in turn activate transcription of antiviral immunological genes, including interferons (IFNs); IFN-alpha and IFN-beta. Responsible for detecting the Picornaviridae family members such as encephalomyocarditis virus (EMCV), mengo encephalomyocarditis virus (ENMG), and rhinovirus. Detects coronavirus SARS-CoV-2. Can also detect other viruses such as dengue virus (DENV), west Nile virus (WNV), and reovirus. Also involved in antiviral signaling in response to viruses containing a dsDNA genome, such as vaccinia virus. Plays an important role in amplifying innate immune signaling through recognition of RNA metabolites that are produced during virus infection by ribonuclease L (RNase L). May play an important role in enhancing natural killer cell function and may be involved in growth inhibition and apoptosis in several tumor cell lines.
Synonyms: MDA-5; RLR-2; MDA5; Hlcd; IDDM19; AGS7; IMD95; SGMRT1
Tractability: Small molecule: a structure with a bound ligand is known. PROTAC: UniProt records ubiquitination sites on it; ubiquitination databases record sites on it; its protein half-life has been measured.
Target class: Enzyme; Hydrolase
Gene: Protein-coding gene on chromosome 2 (162,267,074 to 162,318,684, reverse strand). Ensembl gene ENSG00000115267.
Subcellular location: Cytoplasm; Nucleus; Mitochondrion
Pathways (Reactome):
Immune System: DDX58/IFIH1-mediated induction of interferon-alpha/beta; Modulation of host responses by IFN-stimulated genes; NF-kB activation through FADD/RIP-1 pathway mediated by caspase-8 and -10; Negative regulators of DDX58/IFIH1 signaling; TRAF3-dependent IRF activation pathway; TRAF6 mediated IRF7 activation; TRAF6 mediated NF-kB activation
Disease: Dengue virus activates/modulates innate and adaptive immune responses; Evasion by RSV of host interferon responses; SARS-CoV-1 activates/modulates innate immune responses; SARS-CoV-2 activates/modulates innate and adaptive immune responses
Metabolism of proteins: Ovarian tumor domain proteases; Ub-specific processing proteases
Gene Ontology:
Molecular function: ATP hydrolysis activity; double-stranded RNA binding; identical protein binding; pattern recognition receptor activity; protein binding; protein domain specific binding; ribonucleoprotein complex binding; RNA binding; RNA helicase activity; single-stranded RNA binding; zinc ion binding; ATP binding; DNA binding; hydrolase activity
Biological process: antiviral innate immune response; cellular response to exogenous dsRNA; cellular response to virus; defense response to virus; MDA-5 signaling pathway; negative regulation of viral genome replication; positive regulation of interferon-alpha production; positive regulation of interferon-beta production; positive regulation of interleukin-6 production; positive regulation of response to cytokine stimulus; positive regulation of tumor necrosis factor production; protein complex oligomerization; protein sumoylation; response to virus; cytoplasmic pattern recognition receptor signaling pathway; detection of virus; innate immune response; regulation of type III interferon production; signal transduction
Cellular component: cytoplasm; mitochondrion; cytosol; nucleus
Genetic constraint (gnomAD): Loss-of-function variants: 86 observed, 73.2 expected, observed/expected ratio (o/e) 1.17, 90% interval 0.99 to 1.41. The upper end of that interval is the gene's LOEUF score, 1.41, which puts it in group 5 of 6, group 1 being the genes least tolerant of losing a copy. Missense variants: 945 observed, 909.71 expected, observed/expected ratio (o/e) 1.04, 90% interval 0.98 to 1.1. Synonymous variants: 340 observed, 323.63 expected, observed/expected ratio (o/e) 1.05, 90% interval 0.96 to 1.15.
Gene-disease validity (ClinGen):
ClinGen rates the evidence that IFIH1 causes each of these diseases.
IFIH1-related type 1 interferonopathy (autosomal dominant): Definitive. Any type 1 interferonopathies in which the cause of the disease is a variation in the IFIH1 gene.
Homologues: Orthologues: chimpanzee IFIH1 (99% identical), rabbit IFIH1 (85% identical), pig IFIH1 (85% identical), guinea pig IFIH1 (83% identical), dog IFIH1 (82% identical), rat Ifih1 (80% identical), mouse Ifih1 (80% identical), tropical clawed frog ifih1 (53% identical), zebrafish ifih1 (46% identical), Caenorhabditis elegans drh-3 (21% identical). Paralogues in human: RIGI (29% identical), DHX58 (28% identical).
Diseases named in the same sentence as IFIH1 in open-access papers:
IFIH1 is named in the same sentence as 323 diseases in open-access papers, as found by Europe PMC text mining. Sharing a sentence is not in itself a finding about the gene and the disease. The quoted sentences say what the papers report.
viral infection (429 papers, 2007 to 2026). "This systematic review, following Preferred Reporting Items for Systematic reviews and Meta-Analyses (PRISMA) guidance, explored how IFIH1/MDA5 loss-of-function affects susceptibility to virus infections and/or contributes to inflammatory diseases." (PMID 41695592, 2026). "IFIH1 encodes a protein known as MDA5 (melanoma differentiation-associated protein 5) and is an important immune-related gene involved in the process of virus infections." (PMID 40950552, 2025). "IFIH1 encodes melanoma differentiation-associated protein 5 (MDA5), a ubiquitously expressed cytoplasmic RNA helicase and sensor that is crucial to survival after systemic viral infection by inducing an MAVS-mediated type I IFN immune response." (PMID 41480350, 2025). "GBP protein regulates inflammasome activation, thereby influencing infection mechanisms caused by diverse pathogens.The Ifih1 gene holds immense significance within our bodies due to its implications in autoimmune disorders and viral infections." (PMID 39286150, 2024). "The melanoma differentiation-associated protein 5 (MDA5; encoded by the IFIH1 gene) mediates the activation of the interferon pathway in response to a viral infection." (PMID 37834254, 2023). "Functional variants in the IFIH1 that decrease protein expression and MDA5 activity have been associated with an increased risk of viral infections and the extent of viral disease, including COVID-19." (PMID 37834254, 2023). "In humans, the rs1990760 polymorphism encodes a variant of the IFIH1 gene (NM_022168: c.2836G > A [p.Ala946Thr]) that has been related to different susceptibility to viral infections and autoimmune disorders." (PMID 35060899, 2022). "Ifih1 knockout mice are viable and fertile and show susceptibility to specific viral infections such as picornaviruses." (PMID 34258050, 2021). "Recent human studies have shown that children with inherited MDA5 deficiency or IFIH1 mutation are more susceptible to viral infections." (PMID 33498715, 2021). "The MERS-CoV-shared genes KRT6B and TNFAIP3 had a high p-value associated with SARS-CoV-2, whereas genes such as OAS1-3, IRF9, IRF7, STAT1, PML and IFIH1 were highly associated with host responses to viral infections and type I interferon." (PMID 33301474, 2020). "For example, the protein encoded by the IFIH1 gene is associated with the function of viral infection in the immune system, which affects the survival rate of large yellow croakers." (PMID 29144398, 2017). "The helicase enzyme IFIH1 (also known as MDA5 or melanoma differentiation-associated protein-5) triggers the secretion of interferons in response to viral infection." (PMID 25574400, 2014). "The IFIH1 gene variants that have been associated with higher expression/function might increase the protection against viral infection." (PMID 37834254, 2023). "Besides, MDA5, encoded by IFN-inducible gene (IFIH1 in human), is a key protein sensor to recognize dsRNA produced during viral infections." (PMID 37701443, 2023). "Notably, expression of the A946T variant MDA5 in Ifih1-depleted mouse embryonic fibroblasts (MEFs) resulted in a failure to mount an effective IFN response against virus infection." (PMID 32942706, 2020). "Genetic association between IFIH1 polymorphism and T1D development might be explained by the link of the disease with prior viral infection." (PMID 32974248, 2020). "In particular, Ifih1 was identified across all ages in the hypothalamus; as a receptor for double stranded RNA that responds to viral infections, it could be associated with vulnerability to immunological deficits." (PMID 30568673, 2018). "We propose that, analogous to the severe course of primary influenza infection due to biallelic deficiency of a downstream effector, IRF7, homozygous loss of IFIH1 defines a novel Mendelian immunodeficiency disorder that increases susceptibility to severe viral infections." (PMID 29018476, 2017).
viral infection (continued). "On the other hand, biallelic IFIH1 LoF mutations may be enriched in the entirety of infants with complicated courses of viral infections." (PMID 29018476, 2017). "The genetic association of IFIH1 with T1D may be explained by the reported link with preceding viral infections, as this gene is thought to contribute to the apoptosis of virally infected cells." (PMID 17442111, 2007). "For example, it was hypothesized that the loss of IFIH1 in pangolins may have provided an evolutionary advantage by reducing inflammation-induced damage to host tissues and contributing to the tolerance of viral infections in pangolins." (PMID 36678369, 2022). "Three cases with severe viral infection predisposition were associated with POLR3A, IFIH1, and TLR7XL variations." (PMID 41209815, 2025). "IFIH1 encodes MDA5 (a member of the RIG-I-like receptor family) and is a cytoplasmic sensor of viral infections." (PMID 39844283, 2025). "Severe viral infection predisposition was seen in 3 patients (POLR3A, IFIH1, TLR7XL) and bacterial susceptibility in 3 others (IRF4, IFNGR1, NCSTN)." (PMID 41209815, 2025). "IFIH1’s role in enhancing immune cell activity against viral infections positions it as a significant candidate for developing targeted treatments against HPAIV." (PMID 41042757, 2025). "Based on interaction analysis, miR-324-3p mainly regulated FOSB, MX1, and IFIH1, which can inhibit transcription and replication in the early stages of viral infection, and stimulate to produce the innate immune response." (PMID 38178220, 2024). "The IFIH1 gene located in 2q24.2 is an innate immune receptor that plays a major role in sensing viral infection and in the activation of a cascade of antiviral responses, including the induction of type I interferons and proinflammatory cytokines." (PMID 36979105, 2023). "Variants in IFIH1, a gene coding the cytoplasmatic RNA sensor MDA5, regulate the response to viral infections." (PMID 35060899, 2022). "IFIH1 plays a role in response to viral infection and then participates in nuclear factor kappa-B (NFkB) and interferon regulatory factors (IRF) activation." (PMID 35754802, 2022). "IFIH1, which acts as a cytosolic receptor, is essential for defense against viral infection by sensing double-stranded RNA." (PMID 33777092, 2021). "We then quantified mRNA expression of IFN-β (type I IFN), IFN-λ (type III IFN), select ISGs (OAS2, IFIT1, IFIH1), and the neutrophil attracting chemokine IL-8 (CXCL8), which has been implicated in nasal inflammation during viral infection." (PMID 33811184, 2021). "Most of these DEGs were associated with the host response to virus infection and type I interferons, while others such as IRF9, PML, IRF7, STAT1 and IFIH1 were related to interferon signaling." (PMID 33301474, 2020). "PRRSV and S. suis co-infection also induced the expression of DDX58 and IFIH1, two members of the RIG-I-like receptors (RLRs) family, coding for RIG-I and MDA5, which are cytoplasmic sensors of viral infections." (PMID 27213692, 2016). "Qivr2-2 contains two candidate genes, Itgb6 (integrin beta 6) and Ifih1 (interferon induced with helicase C domain 1), with known functions in the host defense to viral infections." (PMID 22905720, 2012). "Studies that reported associations between viral infection and susceptibility to development T1D as well as autoimmune thyroid disease (ATD), reinforce the IFIH1 gene as a good functional candidate for these autoimmune disorders." (PMID 19961590, 2009). "IFIH1, a 1025 amino acid cytoplasmic protein, protects the host from viral infection by triggering a cellular antiviral and apoptotic response." (PMID 19961590, 2009). "Disruption of ALU/SINE elements with ADAR1 inhibits MDA5/IFIH1 activation against viral infection." (PMID 40724930, 2025).
viral infection (continued). "Previously, it has been reported that in viral infections, m6A often positively correlates with gene expression in immune response pathways, as immune response genes are more active with higher m6A levels, like IFIH1, TNFAIP3, IFIT1 and IFIT2." (PMID 40989927, 2025). "These IFIH1 (MDA5) mutation alleles can activate Mitochondrial Antiviral Signaling Protein-dependent signaling pathways in the absence of viral infection or without bound viral RNA ligands." (PMID 39840076, 2024). "The IFIH1 gene significantly affects the innate immune response to viral infection." (PMID 38926794, 2024). "IFIH1 involved in the antiviral cascades’ activation in response to viral infection (including encephalomyocarditis virus (EMCV) and Mengo encephalomyocarditis virus (ENMG), dengue virus (DENV), west Nile virus (WNV), and reovirus), via induction of Type-1 INF and proinflammatory cytokines." (PMID 32271791, 2020). "RIG-I (Retinoic acid-inducible gene I) encoded by the DDX58 gene in the human genome and MDA5 (Melanoma Differentiation-Associated protein 5) encoded by the IFIH1 gene are known as important protein initiators of earliest immune responses to viral infection." (PMID 31379819, 2019). "Excessive expression of OAS family genes and IFIH1 may limit the magnitude of the response to viruses in the skin of T2DM, leading to a higher risk of viral infection." (PMID 28427244, 2017). "DDX60 positively regulates DDX58 and IFIH1-dependent type I interferon response to viral infection." (PMID 25938420, 2015). "IFIH1 encodes MDA5, a PRR that responds to RNA agonists during virus infection." (PMID 25709093, 2015). "We put forward the hypothesis that loss of IFIH1 and ZBP1 provided an evolutionary advantage by reducing inflammation-induced damage to host tissues and thereby contributed to a switch from resistance to tolerance of viral infections in pangolins." (PMID 32574256, 2020). "Furthermore, the expression levels of OAS genes family were related to DDX58 (RIG-I, retinoic acid-inducible gene I) and IFIH1 (MDA5, melanoma differentiation-associated protein 5), the principal pattern recognition receptor (recognizing dsRNA), and a sensor for viral infection." (PMID 30227596, 2018). "RIOK3 and IFIH1 are involved in IFN-dependent immune responses and play critical roles in sensing viral infections and activating antiviral cascades." (PMID 40783707, 2025). "Among the PRRs, RLRs, including three cytoplasmic RNA helicases (i.e., DDX58/RIG-I, IFIH1/MDA-5, and DHX58/LGP2), are essential for sensing viral RNA and initiating the innate immune response against virus infection." (PMID 37448574, 2023). "The viral infection led to significant overexpression of PRR genes, mainly DDX58, IFIH1, TLR2, and TLR4." (PMID 34937196, 2021). "Two genes (IFIH1 and TRIM21) were upregulated in three viral infections; however, their expression was higher in SARS-CoV-2 compared to IAV, and RSV." (PMID 34276672, 2021). "The components of this minimal gene signature related to IL-6 include DHX58, IFIH1, ISG15, and PNPT1, which it shares with the gene signature observed after yellow fever vaccination." (PMID 33244316, 2020). "The antiviral-ISG, including GBP1, IFI44, IFIH1, IFIT1, MX1, and LY6E, were the most common group of up-regulated genes after influenza infection, yellow fever vaccination, and during febrile episodes of dengue hemorrhagic fever." (PMID 24069471, 2013). "A helicase enzyme, IFIH1, triggers the secretion of interferons in response to viral infections, which in turn up-regulate the MHC class I molecules in beta cells (post-viral infection) leading to T cell response and beta cell death." (PMID 20142867, 2009). "In prior reports of Ifih1 gene duplication or mice carrying MDA5 GOF mutants, which also have increased expression of ISGs and relative protection against viral diseases, the mice have been shown to be more prone to either spontaneous or triggered autoimmunity." (PMID 39896491, 2025).
viral infection (continued). "Select genes that were highly expressed in COVID-19(+) TV specimens compared to COVID-19(+) PU and COVID-19(-) PU control groups play a central role in regulation of innate immune responses and defense to viral infection, including CARD8, IL1A, CD274, TRIM35, IRF7, and IFIH1." (PMID 37026002, 2023). "Hence, IFIH1, TNFAIP3, IFIT1 and IFIT2 were the common immune response genes regulated by m6A during bacterial or viral infection, or LPS treatment." (PMID 35288544, 2022). "Mice with an Ifih1 missense mutation encoding MDA5, developed lupus-like autoimmune symptoms without viral infection." (PMID 33633744, 2020). "In our analyses, there was an increase in IFIH1, SAMHD1, MX1during viral infection, which might be due to the early stage of infection." (PMID 32566414, 2020). "The significant downregulation of interferon signature genes, such as Adar (DRADA), Ddx58 (RIG-I), Ddx60 (DDX60), Stat1 (STAT1), Ifih1 (MDA5), Trim25 (TRIM25), Irf7 (IRF7), and Irf9 (IRF9) in infected Cd47−/− NK cells is consistent with the impaired Cd47−/− NK cell response to viral infection." (PMID 30643501, 2018). "Upon viral infection, intracellular foreign nucleic acids are detected by specific DExD-box RNA helicases of the RIG-I-like receptor (RLRs) family: RIG-I (also known as DDX58), MDA5 (also known as IFIH1), and LGP2 (also known as DHX58)." (PMID 27454487, 2016). "Interestingly, the IFIH1 gene was upregulated about 6 times compared to the PBS group, indicating that CS-gp90@M-M NPs could induce stronger immune responses in secondary immune organs, which could help to prevent viral infections." (PMID 36776397, 2022).